HAX1 (HCLS1 associated protein X-1)
Diseases named in the same sentence as HAX1 in open-access papers (continued):
Sharing a sentence is not in itself a finding about the gene and the disease.
HIV-1 infection (1 paper, 2014). The type species of lentivirus and the etiologic agent of acquired immunodeficiency syndrome (AIDS). "HIV-1 infection was unaffected in the presence of barely detectable levels of DDX3 and TRBP, and high levels of antiviral PKR and Hax1 proteins." (PMID 25188302, 2014).
infarction (1 paper, 2024). A localised pathological necrosis of tissue resulting from obstruction of the blood supply usually by a thrombus, an embolus, or vascular torsion. "Our results indicated that HAX-1 played a protective role in cerebral I/R injury through the inhibition of nervous cell apoptosis in the surrounding areas adjacent to infarction, which was caused by a pyroptosis-induced inflammatory storm." (PMID 38811533, 2024).
invasive breast carcinoma (1 paper, 2019). A carcinoma that infiltrates the breast parenchyma. "Analysis of HAX1 gene in 7 cohorts of invasive breast carcinoma patients using cBioPortal for Cancer Genomics revealed HAX1 altered status in 15% (549/3655) of sequenced cases." (PMID 31093284, 2019).
ischemia (1 paper, 2024). A hypoperfusion of the BLOOD through an organ or tissue caused by a PATHOLOGIC CONSTRICTION or obstruction of its BLOOD VESSELS, or an absence of BLOOD CIRCULATION. "So, we aimed to investigate the effect of HAX-1 on microglial pyroptosis and explore its potential neuroprotective effects in ischemia-reperfusion injury." (PMID 38811533, 2024).
ischemic heart disease (1 paper, 2024). "Hence, HAX1 is an important signal node to consider for cardiac stem cell intervention in the treatment of ischemic heart disease." (PMID 38713406, 2024).
myeloid leukemia (1 paper, 2015). A clonal proliferation of myeloid cells and their precursors in the bone marrow, peripheral blood, and spleen. "Because of the important role of Hax1 in neutrophils we demonstrate here validation of two commercially available research antibodies directed against human Hax1 in the human myeloid leukemia cell line PLB-985 cells." (PMID 27335634, 2015).
renal cell carcinoma (1 paper, 2010). "In a gene expression profiling study utilizing SAGE, HAX1 overexpression was demonstrated to be specifically induced by hypoxia in renal cell carcinoma (RCC) cells." (PMID 20196840, 2010).
skin cancer (1 paper, 2010). "HAX-1 up-regulation in skin cancer samples and cell lines, its involvement in pathology of skin disease and the chromosomal location of the HAX1 gene within the epidermal differentiation complex (chromosome 1q21) suggests its role in maturation of the human epidermis." (PMID 20196840, 2010).
systemic sclerosis (1 paper, 2010). A chronic disorder, possibly autoimmune, marked by excessive production of collagen which results in hardening and thickening of body tissues. "Nuclear localization of HAX-1 has also been observed in systemic sclerosis fibroblasts." (PMID 20196840, 2010).
triple-negative breast carcinoma (1 paper, 2016). An invasive breast carcinoma which is negative for expression of estrogen receptor (ER), progesterone receptor (PR), and human epidermal growth factor receptor 2 (HER2). "In summary, we have provided strong evidence that miR-223 mediates TRAIL sensitivity in triple-negative breast cancer stem cells by regulating the anti-apoptotic HAX-1 gene." (PMID 27618431, 2016).
uveal melanoma (1 paper, 2022). A melanoma derived from melanocytes of the uveal tract. "We were interested in the roles and causal link of HAX-1 in uveal melanoma, so we used chemically synthesized siRNA to knock out HAX-1 expression in mum-2B and C918 cells." (PMID 35602302, 2022). "The effects of HAX-1 on mitochondrial-dependent induction of uveal melanoma cell apoptosis are caused by activating the PI3K/AKT/eNOS signal path and favorable modulation of Bax, caspase 3, and Bcl2." (PMID 35602302, 2022). "For that reason, the present research primarily discusses the expressing features of HAX-1 in uveal melanoma and the causal link affecting cell apoptosis." (PMID 35602302, 2022). "Nevertheless, the role and causal link of HAX-1 in uveal melanoma are still elusive." (PMID 35602302, 2022). "As far as we know, the present research is the first to link HAX-1 to uveal melanoma cell lines and shows that HAX-1 mediated mitochondrion-dependent apoptosis is through the AKT/eNOS pathway." (PMID 35602302, 2022). "In this study, the TCGA database first analyzed survival differences in patients with uveal melanoma with diverse haX-1 expressing levels." (PMID 35602302, 2022). "Those outcomes suggest that HAX-1 induces uveal melanoma cell apoptosis mainly through mitochondrial dependence." (PMID 35602302, 2022). "The survival diversity of uveal melanoma sufferers with diverse haX-1 expressing levels was studied by TCGA database." (PMID 35602302, 2022). "Those discoveries reveal that PI3K/AKT/eNOS/mitochondrial signal path plays a pivotal role in haX-1 induction of uveal melanoma cell apoptosis." (PMID 35602302, 2022). "In this research, the TCGA database was employed to study the survival differences of patients with uveal melanoma with diverse expression levels of HAX-1." (PMID 35602302, 2022). "Those outcomes suggest that HAX-1 can facilitate the development of cancer via regulating uveal melanoma cell proliferation." (PMID 35602302, 2022). "In addition, we also discovered that HAX-1 participates in the modulation of uveal melanoma cellular viability, metastasis, and tumor ring formation via modulating PI3K/AKT/eNOS and triggers UM cell apoptosis via mitochondria dependence." (PMID 35602302, 2022). "In addition, LY294002 also reversed the tumor-forming ability of uveal melanoma cells reduced by HAX-1 knockdown, as well as the apoptosis of uveal melanoma cells induced by HAX-1 in the mitochondria-dependent pathway." (PMID 35602302, 2022). "In addition, haX-1 knockout significantly reduced the pellet-forming ability of uveal melanoma cells compared to the control group." (PMID 35602302, 2022). "Finally, this research demonstrates for the first time that HAX-1 triggers uveal melanoma cell apoptosis via mitochondria dependence via the stimulation of PI3K/AKT/eNOS signal path and favorable modulation of Bax, Caspase 3, and Bcl2." (PMID 35602302, 2022). "We next examined whether HAX-1 triggered apoptosis in uveal melanoma cells." (PMID 35602302, 2022). "Next, we examined whether haX-1 affects uveal melanoma cells through the AKT/eNOS pathway." (PMID 35602302, 2022). "In addition, our team also explored the signaling pathways that might exert impacts on the apoptotic events of uveal melanoma cells triggered by HAX-1." (PMID 35602302, 2022). "However, the molecular mechanism of HAX-1's effect on uveal melanoma has not been studied." (PMID 35602302, 2022).
cancer (30 papers, 2008 to 2025). A tumor composed of atypical neoplastic, often pleomorphic cells that invade other tissues. "MCL1 and HAX1 are key regulators of apoptotic resistance, and their overexpression is associated with poor prognosis and therapeutic resistance in various cancers." (PMID 41154579, 2025). "In turn, overexpression of miR-100 showed increased sensitivity to CIS due to modulation of the HCLS1-associated protein X-1(HAX-1), an inhibitor of mitochondrial apoptosis that maintains mitochondrial membrane potential in cancer cells." (PMID 38132441, 2023). "Alternatively, it seems plausible that nuclear HAX1 can block and/or sequester in inactive complexes some nuclear factor(s), specific to luminal cancers, whose action is linked to metastasis, probably by the regulation of transcription." (PMID 31093284, 2019). "Hematopoietic-substrate-1 associated protein X-1 (HAX-1) has been reported as an anti-apoptosis protein that plays an important role in several malignant tumors." (PMID 29311840, 2017). "Hematopoietic cell-specific protein 1-associated protein X-1 (HAX-1) has been found to be involved in several types of cancer." (PMID 26062578, 2015). "In another study, HAX1 has been shown to bind to the integrin αvβ6, an integrin linked to the aggressive invasive behavior of carcinoma cell and poor clinical prognosis in cancer patients." (PMID 22315598, 2012). "Up-regulation of the HAX1 alternative splice variants in cancer indicates their specific role, but cannot be explained until specific functions would be attributed to the different splice variants and their corresponding putative protein products." (PMID 20196840, 2010). "HAX1 supports the maintenance of the inner mitochondrial membrane potential and prevents caspase activation, and its dysregulation is associated with poor prognosis in several cancers." (PMID 41154579, 2025). "Overexpression of miR-223 downregulates its direct target HCLS1-associated protein X-1 (HAX1) (an anti-apoptotic gene); sensitizes cancer stem cells (CSCs) to TRAIL-induced apoptosis via the mitochondria/ROS pathway; and subsequently activates the effectors caspase-9, caspase-7, and caspase-3." (PMID 39125761, 2024). "Our results suggest that HAX1 over-expression may underlay a novel mechanism to regulate uPAR-induced functions in cancer cells." (PMID 22315598, 2012). "Analysis of the potential variations in HAX1 splicing patterns in tumors may shed some light on the role of splice variants in cancer pathology." (PMID 20196840, 2010). "Results presented here implicate, that the nuclear localization of HAX-1 might be also associated with some types of cancer." (PMID 20196840, 2010). "On the other hand, tyrosine phosphorylation of Grb7 can also be detected when Grb7 binds to HS-1-associated protein X-1 (HAX-1), a cytoskeletal-associated protein that is overexpressed in metastatic cancers, suggesting the potential role of tyrosine phosphorylation of Grb7 in cancer development." (PMID 31083325, 2019). "Cisplatin is a platinum-based compound used in cancer chemotherapy and has been reported to inhibit HAX1." (PMID 40881345, 2025). "Among the SCF complex substrates, the anti-apoptotic proteins MCL1 and HAX1 have been shown to play critical roles in promoting cancer cell survival and therapeutic resistance." (PMID 41154579, 2025). "Subsequent analysis of the impact of HAX1 on the cell transcriptome and analysis of expression in several cancer databases produced coherent results that indicate the unanticipated role of HAX1 in ribosome biogenesis and translation." (PMID 36230905, 2022). "Overexpression of miR-100 showed increased sensitivity to CIS, due to modulation of the HCLS1 associated protein X-1(HAX-1), which is an inhibitor of mitochondrial apoptosis that maintains mitochondrial membrane potential in cancer cells." (PMID 34524579, 2022).
cancer (continued). "In summary, we identified and validated a glycolysis associated five-gene risk signature (NUP85, GPD1, HAX1, GNPDA1 and HDLBP) that can predict the OS of GI Asian cancer patients." (PMID 33663535, 2021). "The role of HAX1 in etiology of different pathologies, including cancer, and its elusive mode of action provides reasons for the comprehensive analysis of HAX1 interactome." (PMID 33146709, 2020). "Growing evidence has demonstrated HAX-1 is overexpressed in many kinds of malignant tumors, particularly affecting proliferation, migration, and apoptosis." (PMID 29311840, 2017). "HAX-1 regulates carcinoma cell migration and invasion by interacting with the β6 subunit and regulates clathrin-mediated endocytosis of αvβ6 integrins." (PMID 26871467, 2016). "HAX-1 regulates carcinoma cell migration and invasion via clathrin-mediated endocytosis of integrin αVβ6." (PMID 26871467, 2016). "Taken together, these results unveil a novel role of HAX1 in the non-canonical NF-κB pathway, and provide an important clue that HAX1 is a potential therapeutic target for the treatment of cancer." (PMID 25275296, 2014). "Subsequent studies from several laboratories including ours have clearly established a crucial role for Hax-1 in cancer cell migration." (PMID 25053987, 2014). "HAX1 is found in clathrin-coated vesicles, and the cytodomain of β6 integrin interacts with HAX1 and is endocytosed, which increases carcinoma migration and invasion." (PMID 22121362, 2012). "HAX-1 (HS1 associated protein X-1, encoded by the HAX1 gene) is an important target of study in the field of cancer research on account of its involvement in regulation of apoptosis and cell migration, key processes in carcinogenesis and metastasis." (PMID 20196840, 2010). "However, HAX1’s impact on CRC metastasis is quite impressive not only in mouse model but also in human cancer tissue." (PMID 38514606, 2024). "HAX-1 promotes the migration and invasion of carcinoma cells by disrupting apoptotic responses." (PMID 33663535, 2021). "However, the role of Hax-1 in cancer cell migration or its role in Rac1-cortactin complex formation, which is known to be required for such migration remains to be characterized." (PMID 25053987, 2014). "The role of HAX1 in inhibition of apoptosis and regulation of cell migration, the two critical processes in carcinogenesis and tumor metastasis, was supported by the fact that HAX1 is highly expressed in different types of human cancers." (PMID 22315598, 2012). "Its involvement in regulation of apoptosis and cell migration along with some data indicating its overexpression in cancer cell lines and tumors suggests that HAX-1 may play a role in neoplastic transformation." (PMID 20196840, 2010). "Recent studies have reported that HAX1 could protect cancer cell via AKT signal pathway." (PMID 34755451, 2021). "Anti-cancer agents targeting HAX-1 may represent a new treatment strategy for TNBC." (PMID 27618431, 2016). "Therefore, HAX-1 protects the cancer cells from drug-initiated apoptotic signaling." (PMID 27880721, 2016). "Increasing our understanding of the specific role of uPAR, hSpry1, and HAX1 in the molecular mechanism of cancer can assist clinically in the development of new tumour markers, which may permit more accurate determination of diagnosis in patients with cancer." (PMID 25937961, 2013). "HAX1 expression is elevated in multiple human cancers, including CRC, and CRC patients with HAX1 overexpression had a significantly poor overall survival." (PMID 38514606, 2024). "Further, HAX1 participates in RAF-MEK-ERK and Wnt pathway, thus targeting HAX1 is appealing for the development of anti-cancer therapeutics." (PMID 38514606, 2024). "Our results reveal upstream regulation layers of HAX1 and illustrates how oncogenic signals from Wnt-EIF3H link to βTrCP-HAX1 axis for promoting ERK activation and tumorigenesis in cancer." (PMID 38514606, 2024).
cancer (continued). "The expression levels of HAX-1 were significantly higher in the cancerous tissues from the patients with CRC, particularly in tissues of an advanced stage of cancer." (PMID 26062578, 2015). "The HAX-1 protein partner, HS1, is highly homologous to cortactin, a cytoskeletal protein frequently overexpressed in cancer." (PMID 20196840, 2010). "Except for the reports demonstrating HAX-1 overexpression in SSC samples and a few cancer cell lines, to date, the only available results concerning its expression in cancer consist of data from microarray and SAGE analyses." (PMID 20196840, 2010). "EIF3H/HAX1 axis promotes CRC tumorigenesis and metastasis in mouse orthotopic cancer model." (PMID 38514606, 2024). "For example, HAX1, RNF2, and CAV1 interact with ABCB1, and these proteins are also prioritized in the top 5 candidate list in VCR study using ProteinRank and involved in chemoresistance in various carcinoma cells." (PMID 26039373, 2015). "The present study provides a mechanism of which HAX1 regulates the non-canonical NF-κB signaling pathway and contributes to the understandings of cIAPs regulation as it closely relates to cancer treatment." (PMID 25275296, 2014). "Although these reports indicate HAX1 overexpression in cancer, their reliability is not as high as in the focused study, so they still need to be verified by more systematic analysis." (PMID 20196840, 2010). "Database analysis of HAX1 expression in correlation to metastasis revealed its significant prognostic value for luminal (ER+) subset while for ER-, despite high overexpression in basal cancers, the expression level had no prognostic value." (PMID 31093284, 2019). "Similar to the action of HAX1, the Smac/DIABLO proteins and Smac mimetic compounds (SM) have been shown to induce the dimer formation of RING finger domain of cIAPs, promote auto-ubiquitination/degradation, and subsequently induce caspase-dependent apoptosis in some cancers." (PMID 25275296, 2014). "However, the structural and functional requirement for Hax-1 in Rac1-cortactin mediated signaling machinery involved in cell migration - especially with reference to cancer cell migration and metastasis - has not been fully understood." (PMID 25053987, 2014). "In our study, HAX1, FLAD1 and NDUFS2, which were positively correlated with DAP3, were reported to play a crucial in mitochondria which could regulate the progression in numerous cancers, indicating that DAP3 may be an important role in OXPHOS, which could affect HCC progression." (PMID 40051634, 2025). "HAX-1 protein has been reported to play a role in apoptosis and cell migration, its overexpression has been detected in cancer cell lines and - mostly by microarray analysis - in tumors, but hitherto, no systematic screen of its expression in cancer has been performed." (PMID 20196840, 2010). "Our preliminary data indicates that both HAX1 and uPAR are simultaneously increased in aggressive (e.g., MDA-MB-231 and PC3) but not in nonaggressive (e.g., MCF-7) cancer cells." (PMID 22315598, 2012).